NF1 (neurofibromin 1)
Diseases named in the same sentence as NF1 in open-access papers (continued):
Sharing a sentence is not in itself a finding about the gene and the disease.
tumor (continued). "Overall, these results demonstrated that Nf1-deficient IF/+ adipocytes have increased collagen and fibrosis-related ECM gene expression preceding tumor formation." (PMID 38799507, 2024). "NF1 is a tumor suppressor that functions as a RAS GTPase activating protein, negatively regulating RAS/MAPK signaling by promoting the inactive GDP-bound form of RAS." (PMID 39472976, 2024). "Various studies have explored the relationship between gene function and clinical manifestations of NF1, including tumor development." (PMID 39211378, 2024). "Functional studies indicate that miR-27a/b also enhances angiogenesis and chemoresistance in tumor cells, making these miRNAs promising candidates for therapeutic targeting aimed at restoring NF1 levels and reducing tumor aggressiveness." (PMID 39594601, 2024). "There was some indication that tumour response was seen less frequently in NF1-related tumours than in sporadic cases (ORR 17% vs. 44%), but the small sample size prevented formal statistical confirmation." (PMID 39409887, 2024). "Treatment should be individualised based on symptoms, tumour extent and progression, NF1 status and patient preference." (PMID 39816384, 2024). "To simulate the TME, we used a three-dimensional (3D) coculture model of immortalized pNF1 tumor cells (Nf1−/−) and primary fibroblasts (Nf1+/−) derived from pNF1 patients." (PMID 39061138, 2024). "Tumor growth rate was significantly increased in the NF1-MET;sgP53 tumors compared to the parental tumors (p-value = 4.7e-4)." (PMID 38480916, 2024). "The clinical management of ONGs in children varies based on the presence of NF1 and the progression of the tumor." (PMID 39835035, 2024). "We have shown that NF1-related tumor cells markedly enhance their glycolytic activity, and a marked rise in glucose avidity is recorded by positron emission tomography when benign PNs progress toward malignancy." (PMID 38995012, 2024). "RNA-seq analysis revealed 127 differentially expressed genes that were shared among NF1-, TSC1-, or TβRII-deficient 4T1 tumor cells compared to the 4T1-C1 control." (PMID 38997291, 2024). "Conversely, more than two thirds of the NF1-mutant cases were detected in tumours from adult patients, predominantly in medullary localisation." (PMID 39256213, 2024). "Experimental animal models of NF1 and in vitro cellular studies have provided significant insights into NF1-related tumor development." (PMID 39217323, 2024). "In contrast, it can be correlated to the evolution of comprehensive treatment algorithms that assign indications and limitations to all therapeutic modalities respecting age, tumor site and size, and NF1‐status." (PMID 38923198, 2024). "In spite of these limitations, our data indicate that prior to tumor formation, mutations in SC/SCP Nf1 are key players in pain-like behaviors." (PMID 38258905, 2024). "Overexpression of IFITM1 in NF1-associated MPNST cells caused a significant decrease in Ras activation (GTP-Ras) and downstream ERK1/2 phosphorylation, indicating that the expression level of IFITM1 was inversely correlated with tumor progression in NF1." (PMID 39273214, 2024). "MPNSTs are strongly associated with internal plexiform neurofibromas (PNs), indicating that tumor progression is a major concern in patients with NF1." (PMID 39273214, 2024).
tumor (continued). "Although tumors are a primary clinical characteristic of NF1, it also produces non-tumor symptoms including pigmentation defects, skeletal abnormalities, stunted growth, cognitive impairments, and behavioral alterations." (PMID 39217323, 2024). "Of the few cytokine/chemokine/growth factor transcripts that differed in SC clusters between controls and Nf1 mutants before tumor formation predicted to uniquely affect neurons, GDNF was the only factor upregulated in SCPs and in nonmyelinating SCs." (PMID 38258905, 2024). "Yet little was known about its effect on rarer NF-1-related neoplasms, such as those arising from the sympathetic nervous system." (PMID 39070150, 2024). "With such fragmentomic-derived biological inferences, we look forward to a synergistic acceleration in our understanding of NF1 tumor progression as tissue informs cfDNA findings and cfDNA findings inform tissue biology." (PMID 38293154, 2024). "Certain factors including tumor location (i.e., circle of Willis), younger age at time of irradiation, NF-1, treatment with an alkylating chemotherapy agent, and higher doses of radiation increase the risk for cerebrovascular complications." (PMID 38912055, 2024). "While NF1 patients have a higher rate of tumor development than the general population, the tumors with the highest penetrance are typically benign." (PMID 39687068, 2024). "They used genetic tests to identify changes in the NF1 gene, which is crucial for tumor suppression." (PMID 39592598, 2024). "For example, patient 31 is a 40-year-old man with GBM, and we detected three mutations— NF1:p.D1485lfs*8, PIK3R1:N/A, and PTEN:p.L23F— in his tumor tissue." (PMID 37920153, 2023). "PA related to neurofibromatosis type 1 (NF1) contain significantly higher percentages of microglia compared to sporadic PA, suggesting a role for a microglia-tumor interplay driven by NF1 related gliomagenesis." (PMID 37901250, 2023). "The proposed recommendations for tumour surveillance for NF1 require a coordinated multidisciplinary approach and significant patient commitment." (PMID 36684394, 2023). "Such alterations resulted in the inhibition of succinate dehydrogenase (SDH) and a consequent stabilization of hypoxia-inducible factor-1 (HIF1) α levels, with the induction of a pseudohypoxic transcriptional program required for NF1-related tumor growth." (PMID 37627552, 2023). "Our findings raised an intriguing question: Does NF1 truly lose its tumor suppressor role in all GBC cells?" (PMID 37147639, 2023). "Another important finding of our study is that PDE4DIP affects KRAS-mutant CRC tumor growth via PKCε-mediated destabilization of NF1." (PMID 37355626, 2023). "By spiking in 10 fmol of a heavy isotope labeled NF1 peptide in tumor lysates, it was possible to quantify NF1 with high sensitivity and linearity." (PMID 37501682, 2023). "Midkine-neutralizing antibodies rescued the Nf1-mutation-induced RGC hyperactivity and inhibited tumor growth in the Nf1OPG mice." (PMID 37891793, 2023). "They first isolated CD133+ cells, which were characterized to be multipotent low grade optic glioma stem cells (o-GSCs) from tumor-bearing NF1+/-GFAPCKO mice." (PMID 38318325, 2023). "In NF-1, the neurofibromin, a tumor-suppressor gene located on chromosome 17q, is inactivated, with the subsequent activation of RAS signaling pathways." (PMID 37830595, 2023).
tumor (continued). "In the case of a multiorgan pattern of relapse, patients were evaluated for the presence of targetable tumor DNA mutations (eg, BRAF, NRAS, and NF1)." (PMID 36852837, 2023). "ΔS was applied to data from high-throughput screening (HTS) of a drug panel tested on NF1−/− tumor cells, using immortalized non-tumor NF1+/− cells as a reference." (PMID 38136356, 2023). "Neurofibromin 1 (NF1) deletion, chromosome 7 enrichment, platelet-derived growth factor (PDGF) amplification, and tumor suppressor PTEN deficiency are discovered in these four types respectively." (PMID 37174078, 2023). "The tumor mutational burden was low in TWM, except in the NF1 mutant forms, and a relatively high frequency of elevated LOH scores suggested frequent homologue recombination deficiency, but this was only confirmed by the mutation signature in one case." (PMID 36980598, 2023). "Lamotrigine, an HCN agonist that is used clinically for treating seizures, rescues Nf1-mutation–induced RGC hyperactivity and inhibits tumor growth in Nf1OPG mice." (PMID 37891793, 2023). "Conversely, participants with PIK3CAmut ctDNA harbouring a neurofibromin 1 (NF1) alteration or high baseline tumour fraction estimate experienced improved PFS upon treatment with taselisib + fulvestrant compared to placebo + fulvestrant." (PMID 36892268, 2023). "Comparative effectiveness between regimens is difficult due to variation in age of onset, location, and extension of tumor, newly diagnosed versus recurrent tumor, NF1 status and radiological definition of disease response and progression." (PMID 37519788, 2023). "NF1 is a tumor suppressor gene that controls cell proliferation, survival and differentiation, and it is inactivated in Recklinghausen disease." (PMID 37959175, 2023). "Based on prior studies implicating the NF-κB pathway in IL-1β–mediated signal transduction, we analyzed this pathway in PDGFB and Nf1 mGBM tumor cell cultures in vitro." (PMID 37733448, 2023). "Patient B (NF2-mutated tumours) on the other hand, had TERT promoter and NF1 mutations in all tumour grades, suggesting that a TERT promoter mutation is not an oncogenic driver, from Grade 2 to 3, as it was also present in the Grade 2 tumour." (PMID 36882706, 2023). "Three patients with metastatic PPGL (two with PV in SDHB and one with PV in NF1) died because of tumor progression." (PMID 37529773, 2023). "Recommendations in this guideline address surveillance, follow-up and management of NF1-asociated tumours." (PMID 36684394, 2023). "In this issue of the JCI, Chen, Giotti, and colleagues investigated loss of ll1b in the immune tumor microenvironment (TME) in GBM models driven by PDGFB expression and Nf1 knockdown." (PMID 37966120, 2023). "Contrary to our expectation that inactivation of these negative regulators would have a greater effect on tumors driven by the weaker KRAS G12C variant, inactivation of Nf1 or KrasWT increased KRAS G12C- and KRAS G12D-driven tumor growth to the same extent." (PMID 37828026, 2023). "Rason KO decreased and Rason OE increased tumor formation in either the Nf1 WT or Nf1 KO background." (PMID 36241718, 2023).
tumor (continued). "One NF1 allele carries a genetic alteration in all cells of a patient with NF1, and a loss of the second NF1 allele (loss of heterozygosity, LOH) results in a complete loss of neurofibromin function and in tumor development." (PMID 37569527, 2023). "Additional to NF1 related tumour treatment and management, regular screening for psychosocial wellbeing and neuropsychological functioning is strongly advised." (PMID 36684394, 2023). "Intriguingly, among these 11 significantly associated genes, Lrp1, Abca1, Map4k4, Vegfa, and Nf1 regulate cell efferocytosis, micropinocytosis, and endocytic activities in DCs, macrophages, and tumor cells." (PMID 37508356, 2023). "NF1-heterozygous mast cells were also found to be activated by c-kit signaling and to promote tumor cell growth by releasing TGF-β, which leads to related clinical studies of tyrosine kinase receptors targeting KIT receptors." (PMID 36831419, 2023). "Neurofibromin products of the neurofibromatosis type 1 (NF1) gene play an important role in tumor suppression." (PMID 36980210, 2023). "Blocking both pathways by fulvestrant (F), a selective ER degrader, together with binimetinib (B), a MEK inhibitor, promotes tumor regression in NF1-depleted ER+ models." (PMID 37501682, 2023). "To measure the amount of NF1 protein in tumor lysates quantitatively with a high degree of sensitivity, we implemented SureQuant, whereby a spiked-in heavy isotopic labeled peptide triggers high-resolution MS2 scan for a matched endogenous peptide." (PMID 37501682, 2023). "Loss of NF1 activity leads to hyperactivation of downstream RAS effectors, thus NF1 is considered a tumor suppressor gene." (PMID 38318325, 2023). "Our study shows that PDE4DIP confers adaptive MEKi resistance and affects tumor growth through a similar NF1/RAS/ERK signaling axis." (PMID 37355626, 2023). "It was found that RNF7 act an imperative role in tumor proliferation and radiation-resistance through inactivating NF-κB and mTOR pathway or assembling tumor suppressive proteins, including NF1, DEPTOR, procaspase-3, p21, p27, NOXA, and BIM." (PMID 36644576, 2023). "On external validation of other cohorts, we find this co-occurrence enriched in recurrent tumors, thus pointing to the early emergence of NF1 inactivation in the NE regions and suggesting that these alterations are important in shaping recurrent tumor." (PMID 37770427, 2023). "To conclude, FCN-159 was well tolerated in patients with NF-1-related PN and demonstrated promising anti-tumor activity." (PMID 37400844, 2023). "Conventionally, the Rho GTPases, such as RAS, are supposed to be oncogenes, and the Rho GAPs, such as NF1, are thought to have tumor suppressive roles." (PMID 36802400, 2023). "Given the aberrant RAS pathway activation induced by loss of NF1, MEK or PI3K inhibitors will most likely form the backbone of any NF1 patient tumor treatment." (PMID 36730269, 2023).
tumor (continued). "New proposals for care of individuals with NF1 have been developed as there are several disease specific issues that differ from the general approach in sporadic tumours, but need to be integrated within routine care." (PMID 36684394, 2023). "For patients with metastatic ILC, mutations in CDH1, NF1, PIK3CA, and TBX3, measured as tumor mutational burden (TMB), are higher than for patients with metastatic IDC." (PMID 37428725, 2023). "In TCGA database analysis, both NF1 and RNF135 showed higher expression levels in the LUAD tumor samples than in the normal samples (P = 1.2E−10 for NF1 and P = 8.8E−04 for RNF135, Mann–Whitney U test)." (PMID 36702236, 2023). "NF1 encodes a negative regulator of RAS signaling, acts as a tumor suppressor gene, and the risk of T-MN is elevated in children with NF1 germline mutations." (PMID 36814285, 2023). "As well as reducing activity toward RAS, switching isoforms to NF1-II in HGG will therefore reduce the ability of tumor cells to dampen their response to constitutive pathway activation as well as ligand-mediated signaling through other receptors." (PMID 35102191, 2022). "A transcriptomic analysis of 76 inherited and sporadic PPGLs identified 2 tumour clusters, one including SDHB, SDHD and VHL-mutated tumours (pseudohypoxic signalling cluster), and one comprising RET and NF1-mutated (kinase signalling cluster) tumours." (PMID 35938916, 2022). "To identify additional genetic alterations that promote the malignancy of NF1-associated tumors, we analyzed the genomic DNA of sNF96.2-GFP parental cells and four subclones of tumor-derived cells." (PMID 35625983, 2022). "The NF1 mutations usually co-existed with PMS2 mutations, and this group included more men and young patients who had a high tumor mutational burden and lateral lymph node metastasis rate." (PMID 35865459, 2022). "When the NGS analysis was performed in parallel on the corresponding cancer tissue, we observed that the mutational status of NF1 and TERT in the EV correlated with that from matched tumor tissue (8/10 and 2/10 patients for NF1 and TERT, respectively)." (PMID 36289852, 2022). "We isolated human primary fibroblasts from normal prostate glands (n = 6) or PCa tumor (n = 6) (marked as NF1-6/CAF1-6), respectively." (PMID 35853880, 2022). "COCA3 was highly relevant to immune response, consistent with the important role of deletions in PTEN and NF1 in facilitating tumor immune evasion (middle)." (PMID 36256461, 2022). "This gene was found in 1990, and its function and significance in tumor formation and other NF1 symptoms have since been extensively studied." (PMID 36090331, 2022). "The consequent increase in intracellular succinate levels stabilizes HIF1α and installs a pseudohypoxic transcriptional program required for NF1-related tumor growth." (PMID 35393510, 2022). "In contrast, the cis-isomer HAS was superior to its trans-isomer HBS on inhibiting a neurofibromatosis type 1 (NF1)-defective tumor cell." (PMID 35978957, 2022). "To further elucidate the contribution of neuronal activity to central and peripheral nervous system tumor development, we focused on NF1, where affected individuals are prone to developing tumors intimately associated with nerves, including OPGs and pNFs32–34." (PMID 35589737, 2022). "In the central nervous system, light-induced stimulation of Nf1-mutant, but not wild-type, retinal ganglion cell neurons increased OPG growth in mice, while light deprivation halted tumor formation in OPG-prone Nf1-mutant mice." (PMID 35188187, 2022).